MFSD2A (MFSD2 lysolipid transporter A, lysophospholipid)
Diseases named in the same sentence as MFSD2A in open-access papers (continued):
Sharing a sentence is not in itself a finding about the gene and the disease.
tumor (12 papers, 2010 to 2025). "An improved response to immunotherapy with anti-PD-1 was linked to increased expression of the major facilitator superfamily domain containing 2A (MFSD2A) in the tumor tissues of AGC patients." (PMID 38928662, 2024). "Loss of Mfsd2a expression in the tumor endothelium results in enhanced BBB leakage, but reduced DHA transport and altered lipid metabolism within metastases." (PMID 29844613, 2018). "However, our data shows that tumor endothelial cells exhibit decreased Mfsd2a expression despite association with pericytes." (PMID 29844613, 2018). "Loss of MFSD2A promotes metastatic tumor growth and survival in the brain microenvironment by altering DHA transport and metabolism, revealing that restoring DHA and/or its metabolites to the tumor microenvironment may be an effective treatment strategy for patients with metastatic brain cancer." (PMID 29844613, 2018). "A potential therapeutic target for improving the efficiency of anti-PD-1 immunotherapy appears to be MFSD2A, which reprograms the tumor microenvironment (TME) to support T-cell activation." (PMID 38928662, 2024). "Recently, MFSD2A has been reported as a novel tumor suppressor gene that plays an important role in modulating the cell cycle and matrix attachment." (PMID 31584009, 2019). "The transporter function of MFSD2A has been shown to play a tumor-suppressive function in non-small lung cancer." (PMID 31584009, 2019). "Together these data suggest that MFSD2A is a novel lung cancer tumor suppressor gene that regulates cell cycle progression and matrix attachment." (PMID 20236515, 2010). "A recent experiment reported that MFSD2A acts as a tumor suppressor in the lung by regulating expression of genes related to cell cycle and extracellular matrix." (PMID 20967283, 2010). "Exogenous expression of MFSD2A in lung cancer cells induced a G1 block, impaired adhesion and migration in vitro, and significantly reduced tumor colony number in vitro (4- to 27-fold, P < 0.0001) and tumor volume in vivo (~3-fold, P < 0.0001)." (PMID 20236515, 2010). "Based on the present findings we can conclude that MFSD2A is a novel suppressor gene in lung cancer acting on tumor growth and development through control of cell cycle profile, matrix attachment, and cell motility." (PMID 20236515, 2010). "The same study further demonstrated that perivascular astrocytes promote Mfsd2a expression in endothelial cells through secreting TGFβ and bFGF, while metastasizing tumor cells can disrupt this signaling pathway to downregulate Mfsd2a and thus facilitate BBB degradation." (PMID 37728789, 2023). "It is enticing to speculate that down-regulation of Mfsd2a may be a strategy utilized by tumor cells to specifically block DHA transport and generally disrupt the BBB via activation of transcytosis events." (PMID 29844613, 2018). "Collectively, these data reveal that loss of Mfsd2a in metastatic tumor endothelial cells leads to decreased uptake of essential fatty acids, especially DHA, which may promote tumor growth and survival in the brain microenvironment." (PMID 29844613, 2018). "Furthermore, we mapped the expression of MFSD2A in the UALCAN database and found that low expression of MFSD2A was significantly correlated with tumor grade and stage (P<0.05)." (PMID 31584009, 2019).
cancer (7 papers, 2010 to 2022). A tumor composed of atypical neoplastic, often pleomorphic cells that invade other tissues. "The effects of MFSD2A expression on cancer cell migration were evaluated in a time-course experiment with the same ECM substrates used in the adhesion assay." (PMID 20236515, 2010). "Hence, we predict that antagonism of the FGF pathway, while potentially effective as an anti-angiogenic strategy for cancer and other pathologies, may lead to unexpected alterations in the BBB and defects in lipid metabolism due to inhibition of Mfsd2a." (PMID 29844613, 2018). "However, transfection of recombinant plasmids in cancer cells where the endogenous MFSD2A gene is strongly downregulated may not be adequate to test the TFs modulating the natural MFSD2A promoter in normal cells." (PMID 21736709, 2011).
neurological diseases (5 papers, 2020 to 2025). "In humans, single nucleotide polymorphisms in MFSD2A and changes in MFSD2A expression levels have been implicated in several severe neurological disorders including autosomal recessive primary microcephaly, intracranial haemorrhage and Alzheimer’s disease." (PMID 37296098, 2023). "Given its increasing recognition as a key regulator of BBB integrity in the pathology of neurological diseases, elucidating the mechanism regulating MFSD2A expression is crucial." (PMID 40649733, 2025). "At present, the research of Mfsd2a in nervous system diseases is limited, and there are many problems need to be further explored." (PMID 34566571, 2021). "What is the relationship between the role of Mfsd2a in promoting brain development, cognition and memory formation and the pathogenesis and prognosis of neurological diseases such as ICH, AD, SAE, MCPH, and intracranial tumor?" (PMID 34566571, 2021). "Since then, Mfsd2a has been involved in the study of neurological diseases related to BBB integrity." (PMID 32612494, 2020). "This article reviewed the current research progress of Mfsd2a in nervous system diseases." (PMID 34566571, 2021). "However, clinical research of Mfsd2a in nervous system diseases is rare." (PMID 34566571, 2021). "More and more importance has been attached to the role of Mfsd2a in maintaining and regulating BBB function and its influence in nervous system diseases." (PMID 34566571, 2021).
infection (3 papers, 2022 to 2025). The state of being infected such as from the introduction of a foreign agent such as serum, vaccine, antigenic substance or organism. "After infection, Mfsd2a, MMP2 and MMP9 showed significantly up-regulation (P<0.05), while CAV-1 expression was significantly down-regulated (P<0.05), indicating that vesicle transport efficiency or barrier permeability was affected." (PMID 40642060, 2025). "Our results also suggested that the interaction of Gal-1 with Syn-2-pseudotyped viruses maximized the interaction between Syn-2 and MFSD2a, as the effect was only observable during the early phase of infection." (PMID 38140682, 2023). "As Gal-1 was found to bind N-glycans on HIV-1 gp120 and the CD4 receptor, we tested if the N-glycosylation status of MFSD2a was important for the effect of Gal-1 during infection." (PMID 38140682, 2023). "In the present study, we extend this association in different cell lines and provide evidence that, using cell fusion and infection assays, Gal-1 increased the binding of Syn-2 with MFSD2a, likely by binding two both cell surface proteins and creating a bridge." (PMID 38140682, 2023). "For in vivo infection, an AAV with Mfsd2a knockdown (2 μl, 1.7*1012 viral genomes/mL) or a control virus (2 μl, 1.3*1012 viral genomes/mL) was administered via intracerebroventricular injection." (PMID 35820896, 2022). "For in vivo infection, an AAV overexpressing Mfsd2a (2 μl, 1.2*1012 viral genomes/mL) or a control virus (2 μl, 1.3*1012 viral genomes/mL) was administered via intracerebroventricular injection using a slow infusion rate of 100 nl/min." (PMID 35820896, 2022).
brain diseases (2 papers, 2016 to 2023). "Considering that Mfsd2a could serve as a therapeutic target for regulating transcytotic mechanisms in CNS ECs, our study may shed light on the development of new therapeutic strategies in BBB-related brain diseases." (PMID 36820986, 2023).
retinopathy (2 papers, 2023 to 2024). "Furthermore, overexpression of Mfsd2a in the retina of mouse models of retinopathy reduced neovascularization and vascular leakage, with a synergistic effect observed when co-treated with DHA." (PMID 39273347, 2024). "Finally, the overexpression of Mfsd2a in the eye was reported to decrease retinal neovascularization and vascular leakage in mouse models of retinopathy and, importantly, co-treatment with DHA had a synergistic positive effect." (PMID 37762391, 2023). "Mfsd2a is emerging lately as a potential therapeutic target and its overexpression in the eye was reported to decrease retinal neovascularization and vascular leakage in mouse models of retinopathy." (PMID 37762391, 2023).
kidney diseases (1 paper, 2023). "Whether the Mfsd2a/LPC pathway is important for protecting the kidney in other types of kidney diseases is not known." (PMID 37467896, 2023).
metabolic disorders (1 paper, 2019). "Our results suggest that altered MFSD2a levels in blood might inform us about metabolic disorders and/or the nutrient transport across other human tissues, which ought to be studied in future." (PMID 31861865, 2019).
MFSD2A also shares sentences with these, for which no sentence is quoted: Anxiety (4 papers); autosomal recessive primary microcephaly (3); intracranial hemorrhage (2); acute kidney injury (1); adenosquamous carcinoma (1); Allan-Herndon-Dudley syndrome (1); amyloid (1); Angelman syndrome (1); cerebral oedema (1); Christianson syndrome (1); Chronic colitis (1); Clear Cell Renal Cell Carcinoma (1); E. coli infection (1); Encephalopathy (1); endothelial dysfunction (1); glioma (1); hemorrhage (1); inflammatory bowel disease (1); lymph node metastasis (1); multiple sclerosis (1); neurodegenerative disease (1); Obesity (1); paraplegia (1); Parkinson disease (1); Rett syndrome (1); Sepsis (1); squamous cell carcinoma (1).